CCND1 (cyclin D1)
Diseases named in the same sentence as CCND1 in open-access papers (continued):
Sharing a sentence is not in itself a finding about the gene and the disease.
cancer (continued). "When the Wnt pathway is activated in cancer, increased β-catenin causes cyclin D1 and c-myc to be activated." (PMID 34215252, 2021). "Cyclin D1 is one of the most important cancer proteins that drive cancer cell proliferation and associate with tamoxifen resistance in BC." (PMID 34589423, 2021). "Loss of USP22 in cancer cells results in defective G1/S cell cycle transition, whereas ectopic cyclin D1 protein partially rescues the aberrant cell proliferation phenotype." (PMID 34072267, 2021). "GO enrichment revealed major biological processes and pathways associated with CCND1/CDK4/PLK1/CD44 in different cancers." (PMID 34063946, 2021). "Previous studies have demonstrated that Cyclin D1 overexpression is the main cause of cancer due to the splice modulation by a polymorphism, A870G, in the donor region of the exon 4/intron boundary." (PMID 33438725, 2021). "For instance, HPV- cancers often have gene copy gains in CCND1 (which encodes for cyclin D1) and amplifications and activating mutations of CDK4." (PMID 34490123, 2021). "And also it can be claimed that any change in Cyclin D1 interaction with these proteins can cause change in its associated pathway which can lead to onset of cancer." (PMID 33438725, 2021). "The CCND1 gene mutation also has been implicated in the development and progression of various cancers." (PMID 34604069, 2021). "Meanwhile, the dysregulation of Cyclin D1 prevalently occurs in the majority of human cancers and is closely linked to shorter survival of patients." (PMID 33964908, 2021). "Dysregulation of Cyclin D1 is frequently linked with various type of cancer in human with diverse histological origin, and thus, it is considered a potential biomarker for diagnosing of different cancers." (PMID 33438725, 2021). "The encoded protein CCND1 plays an important role in cell division, which in turn is a key component of cancer development." (PMID 34081843, 2021). "In cancer cells, the additional amplification of the CCND1 gene, encoding for cyclin D1 (CCND1), is one of the most frequent alterations recorded in human solid neoplasms." (PMID 34445095, 2021). "In cancer cells, the cell cycle is dysregulated by cyclin D1 overexpression, p16 loss, CDK4 mutation, and Rb loss." (PMID 32899250, 2020). "Cyclin B1 and Cyclin D1 control mitosis, cell adhesion, and migration within the cell cycle; hence, they are associated with cancer cell development and metastasis." (PMID 32872198, 2020). "Once into nucleus Cldn-2 retained the transcription factor ZONAB [zonula occludens 1 (ZO-1)-associated nucleic acid binding protein] and Cyclin D1 to enhance cancer cell proliferation." (PMID 33584695, 2020). "Next, we examined the association of CCND1 amplification with clinical outcome for pan-cancer in the TCGA and MSKCC databases." (PMID 32903763, 2020). "The RB pathway has been a focus in cancer therapy, as several components of this pathway, including p16Ink4a, cyclin D1 and RB, are frequently deleted or mutated during the progression of cancer." (PMID 33143142, 2020). "These include well-known cancer-associated genes, such as CCND1 (25 tumors), CDK4 (25 tumors), MDM2 (23 tumors), SETDB1 (23 tumors), ERBB3 (11 tumors), ERBB2 (11 tumors), MYC (10 tumors) and MYCN (five tumors)." (PMID 32025003, 2020). "Induction of cyclin D1 degradation and triggered dephosphorylation of GSK3β, which caused G1 arrest and resulted in inhibiting proliferation of cancer cells." (PMID 33014527, 2020). "Then Kaplan‐Meier survival analysis was used to examine the association between the cyclin D1 expression and cancer‐related deaths." (PMID 32697404, 2020). "We observed significant reduction in the mRNA levels of Kif11, Aurka, Cyclin D1 (Ccnd1), and Cancer susceptibility candidate 5 (Casc5) in Id KD compared to the controls." (PMID 32911668, 2020).
cancer (continued). "Two well-known YAP-TEAD target genes CTGF and CCND1, which encode connective tissue growth factor (CTGF) and cyclin D1, respectively, contribute to the progression of cancer." (PMID 32093160, 2020). "Many downstream genes of STAT3 have been identified in human cancers, including genes associated with cell cycle (cyclin D1 and cMyc), apoptosis (Bcl2-xL and Mcl-1) and metastasis (MMP1 and MMP2)." (PMID 32161621, 2020). "It was previously demonstrated that the overexpression of cyclin D1 was linked to the development and progression of several cancers including bladder, lung, and breast." (PMID 32912025, 2020). "Cyclin D1, a regulatory factor of cell adhesion and migration, has been reported to be associated with cancer cell invasion and metastasis." (PMID 32957430, 2020). "Given that aberrant cell cycle is a hallmark of cancer and Cyclin D1 is a key regulator in G1-S transition of cell cycle." (PMID 32581789, 2020). "The silencing or the inhibition of EIF4G1 caused decreased cyclin D1 and Rb protein levels, cell cycle delay, reduced cell viability, proliferation, clonogenic activity, cancer spheroid formation, as well as increased sensitivity to chemotherapeutic drugs." (PMID 32659970, 2020). "Cyclin D1 overexpression promotes the transformation of a malignant phenotype that is associated with the progression of various types of cancer." (PMID 32104177, 2020). "DNA damage and chromosomal abnormalities cause the overexpression of Cyclin D1 and its accumulation in cancer cell nuclei interfering in cell cycle control, further suggesting the crucial role of the nuclear Cyclin D1 in this type of cancer." (PMID 33317149, 2020). "This in turn activates Tcf/Lef, causing abnormal transcription of the c-myc, c-jun, and cyclin D1 genes, which eventually causes cancers to develop." (PMID 32159210, 2020). "The overexpression of cyclin D1 is also associated with metastasis and poor prognosis in patients with various human cancers." (PMID 32337233, 2020). "Cyclin D1 gene, second important molecule of cell cycle pathway has also been found mutated in almost every human cancer by altering the normal cell cycle pathway." (PMID 32373934, 2020). "Among several gene expressions related to cell growth, epithelial-mesenchymal transition, cancer stemness, and immune regulation, CCND1 expression in CTCs is significantly associated with disease control." (PMID 33299117, 2020). "It has been confirmed that overexpression of CCND1 is associated with a poor prognostic factor in different type of cancers." (PMID 32652519, 2020). "CCND1 gene is a positive regulator of cell cycle, and the overexpression of CCND1 in OSCC has been associated with a shorter survival rate of cancer patients." (PMID 32104177, 2020). "Amplification of the CCND1 gene encoding cyclin D1 is one of the most frequent genomic alterations in human cancers." (PMID 32224897, 2020). "Cyclin D1 is used as a diagnostic marker as it is a commonly overexpressed oncogene in various carcinomas." (PMID 33158043, 2020). "Cyclin D1 also plays a relevant role in cancer, and the variant found in this patient codes for a synonymous change that affects splicing and has been related to abnormal cell proliferation." (PMID 31366136, 2019). "Serving as an important cell cycle driver, the cyclinD1 protein is encoded by the CCND1 gene and it is a prognostic and predictive factor in cancers." (PMID 31934637, 2019). "The PI3K/AKT pathway plays an essential role in cell proliferation in various types of cancer and is closely linked with the adjustment of CCND1 levels." (PMID 31196027, 2019). "In the case of SCCOHT, the critically low level of cyclin D1 caused by SMARCA4 loss is a cancer vulnerability that can also be targeted by the same inhibitors." (PMID 30718506, 2019). "Since Cyclin D1 overexpression is usually a result of genetic mutation, elevated Cyclin D1 expression is a consequence of cancer formation." (PMID 31578445, 2019).
cancer (continued). "The overexpression of cyclin D1 is known to be positively associated with the pulmonary vessel WT in rats and is correlated with the early onset of cancer." (PMID 31200778, 2019). "Investigators from India also tried to explore the association of CCND1 polymorphism and susceptibility to different cancer types including cervical, breast, oral, esophageal, lung, urinary bladder, prostate, and colorectal." (PMID 30361291, 2018). "The goal of this study was to mine whole-exome sequencing data from published studies representing a large number of cases and a plethora of cancer diagnoses to determine the frequency and spectrum of activating CCND1 mutations across human cancers." (PMID 29969496, 2018). "Both myeloid cell leukemia 1 (MCL-1) and Cyclin D1, which are associated with apoptosis and cell cycle regulation, respectively, have been found to be direct targets of miR-193b in other cancers." (PMID 29719597, 2018). "Of note, upregulation of p21 and p27, and downregulation of Cyclin D1 has been closely associated with S-phase arrest in various types of cancer cells including another human TNBC cell line Hs578T." (PMID 30123091, 2018). "Since then many case–control studies have been conducted to explore the potential association between CCND1 SNP (rs9344) and cancer susceptibility." (PMID 30361291, 2018). "The TSA for association between CCND1 polymorphism (rs9344) and overall cancer risk showed that only conventional boundary was crossed by Z-curve, however, it neither crossed the TSA boundary nor the futility area." (PMID 30361291, 2018). "Overexpression of Cyclin D1 is biologically relevant since the gene encoding Cyclin D1 represents the second most frequently amplified locus in the human cancer genome." (PMID 30322449, 2018). "Cyclin D1 is an important mediator of cancer initiation, development, and metastasis and is associated with poor prognosis." (PMID 30402135, 2018). "Overall, in contrast to somatic mutations, CCND1 gene amplification occurred at a frequency of 4.8% (1,419 of 28,769 cases/patients) across all cancers and studies with gene amplification data." (PMID 29969496, 2018). "Defective cyclin D1 degradation by the mutation of Thr-286 contributes to the upregulation of cyclin D1 protein level in several cancers, which results in the significant increase of cyclin D1’s oncogenic potential." (PMID 29554905, 2018). "Cyclin D1, encoded by the CCND1 gene, is a core cell cycle regulator that promotes cellular proliferation and is frequently overexpressed in human cancers." (PMID 29969496, 2018). "Our findings implicate oncogenic c-terminal mutations of CCND1 in the pathogenesis of a subset of human cancers and provide a key resource to guide future preclinical and clinical investigations." (PMID 29969496, 2018). "A total of 12 studies were included in the analysis to evaluate the association between CCND1 polymorphism and cancer risk in Indian population." (PMID 30361291, 2018). "Here we demonstrate that activating, putative driver CCND1 mutations were of low frequency across all cancer types, but were predominantly enriched in uterine endometrioid-type adenocarcinoma." (PMID 29969496, 2018). "Of these, CCND1, which encodes cyclin D1, plays a critical role in the cell cycle machinery (e.g., G1-S transition) and is considered a promising target for cancer therapy." (PMID 29699519, 2018). "EGFR is also present in the nucleus of carcinoma cells, where it transcriptionally regulates several genes, including CCND1 encoding cyclin D1." (PMID 29462882, 2018).
cancer (continued). "Initially, this trial had two separate cohorts; in cohort 1, patients were enrolled according to their ER+/HER2- biomarker status alone, whereas in cohort 2 they were also required to have cancers with cyclin D1 amplification, p16 loss, or both." (PMID 28472136, 2017). "Variations of CCND1 have been detected in many cancers and CCND1 rs9344 polymorphism has been frequently reported to be related with several cancers including NPC." (PMID 28445979, 2017). "The deregulation of CCND1 expression was regarded as a hallmark of cancer by causing continuous abnormal proliferation, thus playing as an oncogene." (PMID 28740507, 2017). "High cyclin D1 expression was significantly associated to PgR positivity and lower grade and ER positivity when ER-positive and ER-negative cancers were tested together." (PMID 28528450, 2017). "STAT3 participates in the initiation, development, and progression of human cancers via inducing downstream genes that encode anti-apoptotic proteins, cell cycle regulators, and angiogenic factors such as Bcl-xl and cyclin D1." (PMID 28187727, 2017). "Upregulation of cyclin D1 in cancer cells is associated with genomic instability and resistance to DNA-damaging drugs." (PMID 29100463, 2017). "Mutation, amplification and overexpression of CCND1 are frequently observed in cancer and have been reported to contribute to tumorigenesis." (PMID 29199958, 2017). "In primary tumors of OSCC patients, STAT3 is constitutively activated and induces expression of cyclin D1, which is associated with cancer cell growth." (PMID 28085115, 2017). "In cancer development and progression, much attention has been focused on the cyclin D1 as one of the oncogenes associated with the regulation of cell cycle." (PMID 28870200, 2017). "As mentioned in the previous research, over-expression of EGFR and cyclin D1 molecular markers is associated with cancer." (PMID 29354245, 2017). "Mutations in CCND1 leading to stable truncated transcripts are associated with increased cell proliferation and shortened survival of cancer patients." (PMID 29199958, 2017). "The constitutive activation of STAT3 has been implicated in the regulation of cancer cell survival (survivin, Bcl-xL), proliferation (cyclin D1/D2) and anti-apoptosis (Bcl-2)." (PMID 28114390, 2017). "It is presumed that high level of the cyclin D1 protein associates with an increased risk of cancers." (PMID 29511472, 2017). "The G870A as a single nucleotide polymorphism (SNP) of CCND1 gene has been investigated in different types of cancers, representing its role in promoting the risk of cancers in several populations." (PMID 29511472, 2017). "Cyclin D1 is deregulated in many types of cancers, but the functional role of cyclin D1 and its association with TGF-β/Smad signaling in CSC regulation is yet to be defined." (PMID 28415588, 2017). "Representative Cyclin D1 target genes were chromosome segregation factors such as AURKB and CENPM that have previously been identified as targets of Cyclin D1 in mouse embryonic fibroblasts and have been implicated in chromosome instability in cancers." (PMID 26883361, 2016). "Overexpression of cyclin D1 found in various cancer cells is associated with the poor prognosis of tumor and metastasis." (PMID 27670681, 2016).
cancer (continued). "Cyclin D1 belongs to the core cell cycle machinery and its overexpression is frequently associated with cancer." (PMID 26950155, 2016). "Among the numerous variants of the CCND1 gene reported in databases, variant c.723G>A (rs9344; p.Pro241=) in exon 4 is one of the most frequently cited in cancer research." (PMID 25436006, 2015). "TTP negatively regulates cell growth in several cancer cell types by inhibiting the stability of many mRNA implicated in cell cycle (c-Myc, cyclin D1), inflammation (TNFα, COX-2), apoptosis (Bcl-2, Mcl-1), and angiogenesis (VEGF)." (PMID 26343742, 2015). "In ER-positive breast cancer, the presence of cyclin D1 amplification has been observed, which causes cell cycle deregulation and results in over-proliferation of cancer cells." (PMID 26059247, 2015). "Epidemiological studies have reported the association between the CCND1 A/A genotype and the risk of various cancers." (PMID 25888980, 2015). "According to the latest published data concerning low-risk cancer susceptibility alleles, the present study examined two CCND1 gene polymorphisms in a cohort of patients with DTC and in the general Polish population." (PMID 25436006, 2015). "CCND1 overexpression was previously found to be associated with shorter patient survival in many cancers and is often correlated with increased risk of metastasis." (PMID 25596748, 2015). "The mutations in the oncogenes KRAS and CCND1 genes are well-established oncogenic mutations in other cancer types." (PMID 26415226, 2015). "Aberrant activity of CDK4/cyclin D1 has been implicated in several cancers, and blocking CDK4/cyclin D1 activity with Ox-1 was previously shown to be an effective anticancer therapy for pRb+ solid tumors." (PMID 26188358, 2015). "Rearrangement of the cyclin D1 gene locus, resulting in protein overexpression, has been associated with prognosis in a variety of malignant tumours, including oral SCC." (PMID 24944679, 2014). "Rather it is the nuclear retention of cyclin D1/CDK kinase that is the cancer predisposing mechanism." (PMID 24429466, 2014). "Overexpression of the cyclin D1 protein is associated with tumorigenesis and is associated with poor outcome in a variety of cancers." (PMID 24438171, 2014). "On the contrary, cyclin D1 (CCND1), implicated in cell cycle regulation and often dysregulated in cancers, and osteopontin (SPP1) a HCC marker, were highly expressed." (PMID 25203629, 2014). "Multiple studies have found a significant association between high levels of cyclin D1 expression and shorter patient survival in many cancers and high expression of cyclin D1 is often associated with increased metastasis." (PMID 25437003, 2014). "Terry Fox Cancer Research Lab in China Medical University previously found that CCND1 genotypes positively associated with other types of cancer in Taiwan." (PMID 25520916, 2014). "The aberrant expression of cyclin D1, a key player in the progression of the cells from G1 to S phase, has been associated with the deregulated cell cycle control in many human cancers." (PMID 24624140, 2014). "Anti-cancer activity of MRBE is associated with ROS-dependent cyclin D1 proteasomal degradation and ROS/ GSK3β-dependent ATF3 expression." (PMID 24962785, 2014). "Overexpression of Cyclin D1 was observed in numerous cancers and proved to be associated with cancer cell proliferation." (PMID 24409330, 2014). "As a result, HPV-positive cancers are thought to be associated with downregulation of cyclin D1 expression." (PMID 23672832, 2013). "Among the cyclin isoforms, cyclin D1 over-expression is most frequently associated with human cancers." (PMID 23516601, 2013). "Cyclin D1 is overexpressed in a variety of cancers and is associated with cancer cell proliferation." (PMID 23840517, 2013). "The association between cyclin D1 expression in cancer cells and RCC prognosis was first evaluated using Kaplan-Meier analysis." (PMID 24137339, 2013).